HNF1A (HNF1 homeobox A)
Diseases named in the same sentence as HNF1A in open-access papers (continued):
Sharing a sentence is not in itself a finding about the gene and the disease.
pancreatic cancer (continued). "Using RT-PCR, Western blot and immunohistochemistry methods, we examined HNF1A gene expression in eight pancreatic carcinoma cell lines and in paired tumor and normal tissue samples from patients with resected pancreatic ductal adenocarcinoma." (PMID 25793983, 2015). "We have observed that inhibition of HNF1A by siRNAs in pancreatic carcinoma cells resulted in a significantly increased cell proliferation." (PMID 25793983, 2015). "For example, HNF1A was noted to promote pancreatic cancer stem cell growth." (PMID 41583511, 2026). "The C allele of the HNF1A rs735396 polymorphism was previously associated with the components of metabolic syndrome in the Tunisian population, as well as altered CRP levels, whereas the T allele was associated with the development of pancreatic cancer." (PMID 35741825, 2022). "There is a controversy for the biological role of HNF1A in pancreatic cancer (PC)." (PMID 34234870, 2021). "Notably, in another study, HNF1A was highly expressed in pancreatic cancer tissues and inhibited the apoptosis of pancreatic cancer cells." (PMID 34234870, 2021). "Interestingly, a study found that HNF1A was highly expressed in pancreatic cancer (PC) tissues, and that overexpression of HNF1A promoted PC cells proliferation and inhibited its apoptosis." (PMID 34234870, 2021). "HNF1A inhibited cell progression in pancreatic cancer cells." (PMID 31949497, 2020). "In order to assess whether HNF1α expression influences these abilities in pancreatic cancer cells, cell viability was measured in HNF1α-silenced AsPC-1 cells and HNF1α-overexpressing HPAC cells." (PMID 33214606, 2020). "MiR-504 negatively correlated with HNF1A, which was highly expressed Pancreatic cancer." (PMID 31949497, 2020). "Our results demonstrate that reduced expression of HNF1α leads to inhibition of pancreatic cancer growth and progression, which indicates that it could be a potential oncogene and target for PDAC." (PMID 33214606, 2020). "HNF1A is a downstream protein in pancreatic cancer, and miR-504 may directly target HNF1A, as predicted by TargetScan." (PMID 31949497, 2020). "Whereas, in pancreatic cancer, HNF1A is a novel oncogene that regulates human stem cell properties." (PMID 31810492, 2019). "Given the importance of HNF1A to pancreatic cancer stem cells, finding ways to prevent this protein from working could lead to new treatments for pancreatic cancer." (PMID 30074477, 2018). "HNF1A/B seem to be good candidates as master regulators of pancreatic differentiation, which at the protein level loses its expression in malignant ductal cells of the pancreas, suggesting its putative role as tumor suppressor in pancreatic cancer." (PMID 27520560, 2016). "However, HNF1A has also been revealed as a specific key regulator of the transcriptome in pancreatic tumor tissues and was suggested as an important tumor suppressor in the pancreas." (PMID 27520560, 2016). "In this study, we have provided some experimental evidence that HNF1A gene may act as a tumor suppressor in pancreatic cancer." (PMID 25793983, 2015). "We next showed a reduced apoptosis rate in HNF1A-inactivated pancreatic carcinoma cells." (PMID 25793983, 2015). "Furthermore, silencing of HNF1A expression raised the rate of pancreatic cancer cell proliferation." (PMID 31685031, 2019). "On the other hand, the mRNA and protein expression level of HNF1A (by both IHC and Western blot analyses) was significantly lower in pancreatic tumors than in the surrounding non-tumor tissues, which is consistent with a potential tumor suppressor role of this gene in pancreatic cancer." (PMID 25793983, 2015). "In the current study, we identified the transcription factor HNF1A as a driver of metastasis in PDAC, introducing a novel pathway in the progression of pancreatic cancer." (PMID 40731412, 2025).
pancreatic cancer (continued). "Conversely, HNF1A overexpression increased PCSC marker expression and tumorsphere formation in pancreatic cancer cells and drove pancreatic ductal adenocarcinoma (PDA) cell growth." (PMID 30074477, 2018). "We then tested HNF1A and MIA2 expression in seven pancreatic cancer cell lines, out of which two (Aspc-1 and Colo-357) expressed both the HNF1A and MIA2 protein." (PMID 25657029, 2015). "HNF1A is not well studied in BC, but is important in colon and pancreatic cancer development and drives PI3K/AKT signaling in esophageal cancer." (PMID 39478117, 2024). "On the other hand, overexpression of HNF1α did not induce any significant change in the aggressiveness of pancreatic cancer cells." (PMID 33214606, 2020). "In addition, another developmental transcription factor, HNF1A, is a novel regulator of pancreatic cancer stem cell properties, and HNF1A + tumors (non-QM, overlap with the exocrine/ADEX subtype) benefit more from FOLFIRINOX than gemcitabine-based treatment." (PMID 34774101, 2021).
hepatocellular carcinoma (39 papers, 2007 to 2026). A malignant tumor that arises from hepatocytes. "By mutating HNF1A by small interfering RNA in hepatocellular carcinoma cells increases overexpression of numerous genes translating cell cycle and angiogenesis regulators, growth factors receptors and components of translational machinery." (PMID 33580750, 2021). "One of the key events during the progression of hepatocellular carcinoma is the loss of expression of master genes of epithelial/hepatocyte differentiation, such as HNF4α and HNF1α, that play a pivotal role in the restraint of inflammation, fibrosis, and EMT." (PMID 31543815, 2019). "Somatic mutations in HNF1A in hepatocellular carcinoma from the COSMIC database indicated that the number of non-silent mutations in the homeobox domain is significantly greater than other domains (p = 8.64 × 10−6)." (PMID 27469031, 2016). "Although the protein expression of mutants was clearly detected in hepatoma cells, functional studies demonstrated the opposite effects of wild-type and mutant allele of HNF1A on hepatoma cell growth and migration." (PMID 27469031, 2016). "Next, we examined the cellular distribution of HNF1A in hepatoma cells transduced with wild-type HNF1A as well as S247T-mutated HNF1A." (PMID 27469031, 2016). "Somatic mutations of HNF1A gene have been reported in hepatoma, colon cancer and endometrial cancer." (PMID 25793983, 2015). "HNF1A silencing by siRNA in hepatocellular carcinoma cells induced overexpression of several genes encoding growth factor receptors, components of the translational machinery, cell cycle, and angiogenesis regulators." (PMID 25793983, 2015). "In functional in vitro studies, the HNF1A rs1169288C p.L27 polymorphism could significantly increase the ABCC1 promoter activity in human HepG2 hepatocellular carcinoma cell line and HEK293 kidney cells." (PMID 29066969, 2017). "Furthermore, HNF1A level has been shown to be associated with differentiation of hepatocellular carcinoma (HCC)." (PMID 25953102, 2015). "Specifically, it acts as a competitive endogenous RNA in gastric cancer by sponging miR-30b-3p and, when regulated by HNF1α, mitigates hepatocellular carcinoma malignancy by enhancing SHP-1 phosphatase activity." (PMID 40034693, 2025). "Enhanced activities from preS1, preS2/S, core promoter, and Enh- II as a result of binding of liver enriched TFs, including HNF1α, HNF3α and HNF4α were observed using hepatoma cells." (PMID 33810128, 2021). "TNF-α and IFN-γ induced IL-32 in primary human hepatocytes and hepatoma cells that regulate the transcription of HBV core promoter by downregulating HNF1-α and HNF4-α." (PMID 33868257, 2021). "In fact, the knockdown of both Hnf-1α and Hnf-1β decreased the expression of Angptl8 protein in both mouse hepatoma cells and mouse primary hepatocytes." (PMID 32561878, 2020). "STAT3 protein together with IL6, HNF4A, HNF1A, and three microRNAs constructed a feedback loop, which regulates oncogenesis of hepatocellular carcinoma (HCC)." (PMID 31219249, 2019). "Liraglutide, a once-daily glucagon-like peptide-1 (GLP-1) agonist, was found to suppress PCSK9 expression via a hepatocyte nuclear factor 1 alpha (HNF1α)-dependent mechanism in the human hepatoma cell line, HepG2." (PMID 31706300, 2019). "Studies showed that cultured cells derived from differentiated hepatoma cells express HNF1α, whereas cultured dedifferentiated hepatoma cells express HNF1β instead of HNF1α." (PMID 26464794, 2015). "A previous study conducted in hepatoma cell lines has found elevated level of cyclin D1 in response to HNF1A inactivation." (PMID 25793983, 2015). "In contrast to other hepatic tumors, FNH does not commonly express beta-catenin (CTNNB1) or HNF1α mutations, which are seen in hepatocellular carcinomas and adenomas, respectively." (PMID 40448211, 2025).
hepatocellular carcinoma (continued). "However, RNA-Seq data for HNF4A siRNA knockdown (KD) in human hepatoma cell line (Huh7) cells suggested that the HNF4A mediated decrease in the expression of HNF1A and other genes is related to binding activity, the lipid and cholesterol metabolism pathways." (PMID 35327967, 2022). "They found that HNF1α could inhibit the proliferation of hepatocellular carcinoma cells, promote the expression of liver-specific genes in hepatocellular carcinoma cells, and abolish the tumorigenicity of hepatocellular carcinoma cells in vivo." (PMID 35096588, 2021). "It was also found that HNF1α could inhibit the activation of TGFb/Smads pathway in hepatocellular carcinoma cells and affect the growth and differentiation of hepatocellular carcinoma cells." (PMID 35096588, 2021). "Besides, genes down‐regulated in the diethylnitrosamine treatment‐induced or E2F1 overexpression‐induced hepatocellular carcinoma models and HNF1A knockout model of type 1 diabetes are also overrepresented, supporting the liver protective roles of metformin." (PMID 32529766, 2020). "It has been suggested that bi-allelic inactivation of HNF1A may be an early step in the development of some hepatocellular carcinomas." (PMID 27469031, 2016). "Third, we tested the effects of overexpression of HNF1A on hepatoma cell growth." (PMID 27469031, 2016). "Second, we evaluated the effects of knockdown of HNF1A on hepatoma cell growth and migration." (PMID 27469031, 2016). "In hepatocellular carcinoma (HCC), TNFα-induced NF-kB signaling downregulates HNF1α, thereby inhibiting miR-194, and results in tumorigenesis." (PMID 34771521, 2021). "Transfections of HNF4A, HNF1A and FoxA3 suppressed hepatocellular carcinoma (HCC) cell proliferation, suggesting tumor suppressive roles of FoxA3 in HCC." (PMID 32151057, 2020). "In other studies, researchers have found that the combination of HNF1A, HNF4A and fork head box protein A3 (FOXA3) can reprogram hepatocellular carcinoma cells into hepatocyte-like cells." (PMID 34234870, 2021). "It has been found that the simultaneous expression of HNF1α, HNF4α and FOXA3 can transform hepatoma cells into hepatocyte-like cells." (PMID 35096588, 2021). "It has been well known that the HNF family is extensively involved in human AGT regulation, for example, HNF-1α and HNF-4 can bind to the AGT promoter sequences and activate AGT expression in human hepatoma cells." (PMID 29053707, 2017). "Furthermore, the combined expression of HNF1A, HNF4A, and forkhead box protein A3 (FOXA3) was noted to inhibit hepatocellular carcinoma cell growth." (PMID 41583511, 2026). "Interestingly, enforcing expression of HNF4α, in cooperation with Forkhead Box Protein A3 (FOXA3) and Hepatocyte Nuclear Factor 1-Alpha (HNF1α), could even reverse the hepatocellular carcinoma (HCC) cells into normal hepatocyte-like cells." (PMID 36249028, 2022). "Moreover, we also recently have reported that the combination of HNF1A, HNF4A, and FOXA3 synergistically reprograms the hepatocellular carcinoma (HCC) cells to hepatocyte-like cells." (PMID 34141708, 2021). "Mechanically, the exogenous expression of HNF1α, HNF4α and FOXA3 in hepatocellular carcinoma cells promotes the endogenous expression of a variety of hepatocyte nuclear factors, including C/EBP, thus promoting the transformation of hepatocellular carcinoma cells into hepatocyte-like cells." (PMID 35096588, 2021). "However, in hepatoma cells, glucose-induced AGT augmentation is mediated predominantly through HNF-1α- and HNF-4-dependent pathways." (PMID 29053707, 2017). "For example, biallelic somatic alterations of HNF1A were present in 60% of hepatocellular adenomas and in rare cases of hepatocellular carcinomas in non-cirrhotic liver." (PMID 25793983, 2015). "HL secretion was only observed with hepatoma cell lines that express HNF1α or HNF1β mRNA, but not all cell lines with detectable HNF1α or -β expression do also secrete HL." (PMID 17428321, 2007).
hepatocellular carcinoma (continued). "It's worth noting that the combination of three liver transcriptional factors (TF), HNF1A, HNF4A, and FOXA3 transduced the Hepatocellular carcinoma (HCC) cell lines to more stably suppress cell proliferation." (PMID 34234870, 2021). "To further our understanding of CYP enzymes and to advance the use of hepatoma cells as replacements for primary hepatocytes, we investigated the expression and enzyme activity of CYP3A4 in Hep G2 cells following the delivery of hepatocyte nuclear factor-1 alpha (HNF1α) using a lentivirus system." (PMID 24733486, 2014). "Biallelic mutations of HNF1A have been identified in about 35% of hepatocellular adenomas (HCA), rare benign liver tumors usually occurring in young women under oral contraceptives, and in rare cases of hepatocellular carcinomas developed in non-cirrhotic liver." (PMID 21975049, 2011). "Biallelic inactivating mutations of HNF1A have been frequently identified in hepatocellular adenomas (HCA), rare benign liver tumors usually developed in women under oral contraceptives, and in rare cases of hepatocellular carcinomas developed in non-cirrhotic liver." (PMID 21975049, 2011).
hepatocellular adenoma (30 papers, 2011 to 2026). A benign epithelial neoplasm arising from the hepatocytes. "Biallelic variants in HNF1A can cause hepatocellular adenomas, while variants in HNF4A can cause Fanconi renotubular syndrome and are associated with SHBG levels." (PMID 39666780, 2024). "Hepatocellular adenomas (HAs) are tumors that can develop under different conditions, including in patients harboring a germline mutation in HNF1A." (PMID 39408812, 2024). "HNF-1α-inactivated hepatocellular adenomas have the lowest potential for bleeding and the lowest risk of malignant transformation." (PMID 37190288, 2023). "HNF1A codes for the transcription factor HNF1α, which regulates hepatocyte functions; it is frequently mutated in benign hepatocellular adenomas and its inactivation indicates a role as a tumor suppressor." (PMID 33572923, 2021). "In patients, SigR1 overexpression seems to be correlated to the loss of HNF1α in hepatocellular adenomas." (PMID 32784704, 2020). "Currently, four subtypes of hepatocellular adenomas are recognized: inflammatory, hepatocyte nuclear factor 1 alpha (HNF-1α) mutated, β-catenin mutated and unclassified." (PMID 27526937, 2016). "Decreased LFABP has been found to be a hepatocellular adenoma marker specific to a subtype HNF1α mutation, similar to our earlier observation in carcinogen-induced liver tumors in zebrafish." (PMID 24626481, 2014). "It has been suggested that inactivating mutations in HNF1α and activating mutations in β-catenin within the hepatocellular adenomas serve to classify clinical and prognostic factors such as progression to carcinoma as proposed for β catenin mutations." (PMID 25566190, 2014). "In 2002, we identified HNF1A, as the first driver gene inactivated by mutation in hepatocellular adenomas." (PMID 23401783, 2013). "HNF1α-mutated hepatocellular adenomas exhibit fat and a hypovascular pattern on MRI." (PMID 39199678, 2024). "Moreover, HNF1A-mutated hepatocellular adenomas (H-HCAs) were phenotypically categorized by marked steatosis in which the mTOR pathway was aberrantly activated." (PMID 34771521, 2021). "HNF1A‐MODY is associated with HNF1A‐inactivated hepatocellular adenoma (H‐HCA) formation." (PMID 31483937, 2019). "According to recent studies HCAs are currently categorized in to four distinct genetic and pathologic subtypes: inflammatory hepatocellular adenomas, hepatocyte-nuclear-factor-1-alpha (HNF-1α-mutated) hepatocellular adenomas, β-catenin-mutated hepatocellular adenomas, and unclassified adenomas." (PMID 23606972, 2013). "According to recent studies HCAs are currently categorized in four distinct genetic and pathologic subtypes as follows: inflammatory hepatocellular adenomas, hepatocyte-nuclear-factor-1-alpha- (HNF-1α-mutated) hepatocellular adenomas, and β-catenin-mutated hepatocellular adenomas." (PMID 23606972, 2013). "Moreover, while HNF1A inactivation is known to be frequent in hepatocellular adenoma, somatic mutations in this gene are relatively a rare event in HCC and very often bound to specific etiological characteristics such as absence of cirrhosis and viral infection." (PMID 31570105, 2019). "One lesion was a hepatocellular adenoma (HA) belonging to the hepatocyte nuclear factor 1α [HNF1α] inactivated subtype." (PMID 38254797, 2024). "At CEUS, HNF-1α-inactivated hepatocellular adenomas are homogeneously hyperenhancing in the arterial phase." (PMID 37190288, 2023). "In hepatocellular adenomas, efficient silencing of FABP1 can be caused by biallelic inactivation of hepatocyte nuclear factor 1α (HNF1A) which occurs in 35–40% of cases." (PMID 35951102, 2022). "Although only two HCV infected HIL mice in this study developed hepatocellular adenomas, our data demonstrates that both HNF1a inactivated and inflammatory adenomas can develop in this model." (PMID 28886065, 2017).
hepatocellular adenoma (continued). "Light has been shed on the genotype/phenotype correlation in hepatocellular adenoma (HCA) recognizing HNF1α-inactivated HCA (H-HCA), inflammatory HCA (IHCA), and β-catenin-activated HCA (b-HCA)." (PMID 23533787, 2013). "Biallelic inactivation of HNF1A has been previously reported to lead to aberrant activation of signalling pathways involved in tumorigenesis in human hepatocellular adenomas." (PMID 21625565, 2011). "HNF-1α-inactivated hepatocellular adenomas (previously called steatotic adenomas) account for 35–50% of adenomas and are usually seen in females with oral contraceptive use and in patients with autosomal dominant maturity onset diabetes of the young, type 3 (MODY3)." (PMID 37190288, 2023). "Scientific research over the period of three decades has reported it as an important player in various liver malignancies such as hepatocellular cancers (HCCs), hepatocellular adenoma (HA), and a more specific HNF-1α-inactivated human hepatocellular adenoma (H-HCAs)." (PMID 31685031, 2019). "This may be due to the fact that there are many types of adenomas in humans, such as inflammatory hepatocellular adenoma, HNF-1α-mutated hepatocellular adenoma or the β- catetin- mutated hepatocellular adenoma, not distinguished in dogs." (PMID 31412920, 2019). "Previously, Rebouissou and colleagues have established clinical-based study spanning over a decade including 40 human hepatocellular adenomas (HCAs) that are linked with the inactivated or mutated HNF-1α expression, 25 non-steatotic non-tumor livers, and 11 steatotic non-tumor livers." (PMID 31685031, 2019). "Light has been recently shed on the genotype/phenotype correlation in hepatocellular adenoma (HCA) leading to the identification of four different subtypes: HNF1α-inactivated HCA (H-HCA), inflammatory HCA (IHCA), β-catenin activated HCA (b-HCA), and unclassified HCA." (PMID 23533787, 2013). "Unlike previously reported cases, our patient uniquely demonstrated the coexistence of cirrhosis and an HNF1A-inactivated hepatocellular adenoma, a combination not described before in this setting." (PMID 41609269, 2026).